LINC02975 (long independently transcribed non-coding RNA 2975)
Synonyms: AL161785.1
Gene: Long non-coding RNA gene on chromosome 9 (129,282,426 to 129,347,468, forward strand). Ensembl gene ENSG00000224307.
Diseases named in the same sentence as LINC02975 in open-access papers:
LINC02975 is named in the same sentence as 1 disease in open-access papers, as found by Europe PMC text mining. Sharing a sentence is not in itself a finding about the gene and the disease.
LINC02975 shares sentences with these, for which no sentence is quoted: gastric cancer (1 paper).